SLC35G4 (solute carrier family 35 member G4)
Description:
Mediates choline transport, although the underlying transport mechanism remains to be elucidated.
Synonyms: AMAC1L1; SLC35G4P
Tractability: Antibody: UniProt predicts a signal peptide or a membrane-spanning region.
Gene: Protein-coding gene on chromosome 18 (11,609,596 to 11,610,612, forward strand). Ensembl gene ENSG00000236396.
Subcellular location: Membrane
Gene Ontology:
Molecular function: choline transmembrane transporter activity
Biological process: choline transport
Cellular component: membrane
Genetic constraint (gnomAD): Loss-of-function variants: 12 observed, 14.84 expected, observed/expected ratio (o/e) 0.81, 90% interval 0.52 to 1.31. The upper end of that interval is the gene's LOEUF score, 1.31, which puts it in group 5 of 6, group 1 being the genes least tolerant of losing a copy. Missense variants: 390 observed, 349.25 expected, observed/expected ratio (o/e) 1.12, 90% interval 1.03 to 1.21. Synonymous variants: 177 observed, 156.34 expected, observed/expected ratio (o/e) 1.13, 90% interval 1 to 1.28.
Homologues: Orthologues: macaque SLC35G6 (91% identical), dog SLC35G6 (87% identical), mouse Slc35g3 (81% identical), rat Slc35g3 (80% identical), Drosophila melanogaster CG5281 (15% identical). Paralogues in human: SLC35G5 (93% identical), SLC35G6 (91% identical), SLC35G3 (91% identical), SLC35G2 (29% identical), SLC35G1 (19% identical).
Diseases named in the same sentence as SLC35G4 in open-access papers:
SLC35G4 is named in the same sentence as 1 disease in open-access papers, as found by Europe PMC text mining. Sharing a sentence is not in itself a finding about the gene and the disease. The quoted sentences say what the papers report.
hearing loss (1 paper, 2025). "Interestingly, mutations were also observed in SLC35G4, a predicted nucleotide sugar transporter, and TMEM132E, a transmembrane protein associated with nonsyndromic hearing loss." (PMID 41488087, 2025).